IMP3 (IMP U3 small nucleolar ribonucleoprotein 3)
Diseases named in the same sentence as IMP3 in open-access papers (continued):
Sharing a sentence is not in itself a finding about the gene and the disease.
prostate carcinoma (7 papers, 2010 to 2025). A carcinoma that arises from epithelial cells of the prostate gland. "In the present study, we identified circIMP3, a circular RNA derived from the IMP3 gene, as being significantly upregulated in prostate cancer tissues and patient blood samples." (PMID 41561631, 2025). "This study aims to investigate the role of circIMP3, derived from the IMP3 gene, in prostate cancer development." (PMID 41561631, 2025). "In contrast, in another tumour entity, prostate carcinoma, increased IMP3 expression of the primary tumour was shown in the presence of distant metastasis." (PMID 37627115, 2023). "In prostate cancer, IMP3 is overexpressed, and it accelerates the cancer’s progression by increasing SMURF1-mediated PTEN ubiquitination, which in turn activates PI3K/AKT/mTOR signaling." (PMID 35366242, 2022). "Additionally, IMP3 was expressed in the reactivated stroma, in the prostate cancer, suggesting that IMP3 has influence in stromal‐epithelial interaction and fibroblast‐to‐myofibroblast differentiation." (PMID 34035433, 2021). "Therefore we had expected a prognostic value of IMP3 in prostate cancer, as has already been shown in other malignancies." (PMID 20591150, 2010). "Although IMP3 is overexpressed in a significant proportion of prostate cancer cases, which might be of importance for novel therapeutic approaches, it does not appear to possess any immediate diagnostic or prognostic value, limiting its potential as a tissue biomarker for prostate cancer." (PMID 20591150, 2010). "Immunohistochemical stainings for IMP3 were performed on tissue microarray (TMA) organized samples from 507 patients: 31 normal prostate tissues, 425 primary carcinomas and 51 prostate cancer metastases or castration-resistant prostate cancers (CRPC)." (PMID 20591150, 2010). "Recent studies have also revealed another ribosome component, IMP3, could promote invasion of both CRC and prostate cancer cells." (PMID 36816947, 2023). "We cannot exclude a possible minor prognostic value of IMP3, but on the basis of our data we assume that IMP3 is very unlikely to represent a strong prognostic biomarker in prostate cancer." (PMID 20591150, 2010). "Although IMP3 is overexpressed in prostate cancer, preferentially of higher Gleason scores, it does not have the same outstanding diagnostic and prognostic value for prostate cancer, as it has for other malignancies." (PMID 20591150, 2010). "The primary prostate carcinomas (n = 425) 16.7% (n = 71) showed no IMP3 expression, 69.2% (n = 294) did show weak staining, 13.4% (n = 57) moderate and 0.7% (n = 3) strong staining for IMP3 (median = 1)." (PMID 20591150, 2010).
hepatocellular carcinoma (6 papers, 2010 to 2024). A malignant tumor that arises from hepatocytes. "Moreover, IMP-3 was shown to promote proliferation of human leukemia cells and invasion of hepatocellular carcinoma." (PMID 26796627, 2016). "U3 small nucleolar ribonucleoprotein (IMP3) and protein kinase C alpha (PRKCA) had been previously linked to aggressiveness and metastasis in a variety of tumor types, including breast, colon, renal cell, lung, ovarian, and hepatocellular cancer." (PMID 20520718, 2010). "This is corroborated by the fact that enhanced IMP3 expression was found in over 58% of end-stage renal cell carcinoma tumors (stages III and IV), and more than 40% in hepatocellular carcinoma (HCC)." (PMID 38328550, 2024).
ovarian carcinoma (6 papers, 2014 to 2023). A malignant neoplasm originating from the surface ovarian epithelium. "So far, only one study has examined the value of IMP3 expression in the differential diagnosis of ovarian carcinomas, and the authors suggested IMP3 to be an additional diagnostic marker for ovarian CCC." (PMID 36740684, 2023). "IGF2BP3 (also known as IMP3), also expressed in ovarian cancer cells, is a part of the IGF2BP family, which is associated with the development, progression and prognosis of ovarian cancer." (PMID 34794452, 2021). "As recently reported, knockdown of IMP3 decreased cell proliferation, migration, and invasion, and increased the sensitivity to platinum in ovarian cancer through increased expression of hCTR1." (PMID 26837693, 2016). "Although IMP3 expression, which is associated with tumor growth, progression, and unfavorable prognosis, has been explored in a number of human malignancies, only two studies on immunohistochemical analysis for IMP3 in ovarian cancers have been published." (PMID 25038792, 2014). "IMP3 has also been used as a prognostic marker for all ovarian cancer patients in our routine pathology practice, during which IMP3 overexpression was sometimes observed in normal-appearing tubal mucosa as well as in STIC cases." (PMID 25014991, 2014). "A more prominent increase of IMP3 signatures is observed in patients with high-risk factors, such as BRCA mutations or first degree family history of ovarian cancer, and in patients with PSC." (PMID 25014991, 2014). "Therefore, the significance of IMP3 expression in ovarian cancer, particularly in CCC, requires further analysis." (PMID 26837693, 2016). "However, the high expression of IMP2 and IMP3 in ovarian carcinomas may gain further interest since IMP proteins are potential therapeutical targets." (PMID 36740684, 2023). "However, the high expression of IMP2 and IMP3 could be of predictive value in ovarian carcinomas since IMP proteins are potential therapeutical targets." (PMID 36740684, 2023). "The authors investigated 336 ovarian carcinomas (including 132 CCC, 103 HGSC, and 116 EC) and found IMP3 positivity in 86% of CCC, 23% of HGSC, and 2% of EC cases." (PMID 36740684, 2023).
pancreatic cancer (6 papers, 2015 to 2025). "When simultaneous immunohistochemical staining for IMP3 and mesothelin was performed on pancreatic cancer, chronic pancreatitis, and normal pancreatic tissues, the sensitivity was 85% and specificity was 90%." (PMID 40722532, 2025). "IMP3, a member of RBPs, was found upregulation in several cancers, such as triple negative breast cancer, gastric cancer, pancreatic cancer, and almost all gynecological tumors." (PMID 34154626, 2021). "Using siRNA-mediated inhibition, the current study demonstrated that knockdown of IMP3 significantly reduced migration, invasion, and adhesion of pancreatic cancer cells." (PMID 25886367, 2015). "Our results demonstrate that IMP3 is involved in facilitating the pro-metastatic behavior of a subset of pancreatic cancer cells." (PMID 25886367, 2015). "In this study, we demonstrated that knockdown of IMP3 impedes motility, invasion, and matrix adhesion of pancreatic cancer cells." (PMID 25886367, 2015). "Taken together, our results showed that IMP3 expression promotes matrix adhesion, motility and invasion of pancreatic cancer cells by enhancing CD44 and KIF11 expression." (PMID 25886367, 2015). "The observed decrease in motility, invasion, and matrix adhesion of Hs766T following IMP3 knockdown suggests that IMP3 facilitates the pro-metastatic behavior of a sub-set of pancreatic cancer cells." (PMID 25886367, 2015). "Next, we assessed the effect of IMP3 depletion on the adhesion of pancreatic cancer cells to proteins in the extracellular matrix (ECM)." (PMID 25886367, 2015). "The current review study identifies 22 IHC biomarkers as diagnostic tools for pancreatic cancer that embrace: Pentraxin-3, ENO1, REG4, POSTN, CA125, CA242, Galectin-1, Galectin-9, Maspin, pVHL, MUC1, MUC5AC, THBS2, LTBP2, CPA4, IMP3, CD13, Dkk1, KOC, S100P, Mesothelin, PAM4." (PMID 34988027, 2021). "Given the poor efficacy of currently available treatments in PDAC, pharmacologic inhibitors of IMP3 may represent a viable therapeutic strategy by altering pancreatic cancer cell behavior and halting/delaying pancreatic tumour metastasis." (PMID 25886367, 2015). "Analyzed IHC biomarkers that can differentiate pancreatic cancer from chronic pancreatitis encompass REG4, POSTN, CA242, Galectin-1, maspin, pVHL, IMP3, CD13, and PAM4." (PMID 34988027, 2021).
serous carcinoma (6 papers, 2014 to 2024). "In a subsequent study on 401 cases, the same authors found 78% of serous carcinomas, 57% of clear cell carcinomas and 15% of endometrioid carcinomas IMP3 positive by using a combined scoring system for intensity and percentage of expression." (PMID 36740684, 2023). "In endometrial lesions IMP3 expression has been found in benign endometrium, atypical endometrial hyperplasia, and endometrial carcinomas, with the highest expression in serous carcinomas." (PMID 36740684, 2023). "IMP3 has been shown to be expressed in a majority (>90%) of serous carcinomas 21,22." (PMID 30550483, 2019). "The serous carcinoma-associated markers p16 and IMP3 may be expressed in clear cell carcinoma, and are not particularly useful in the distinction between these 2 tumor types 17,18,21,22,62,63." (PMID 30550483, 2019). "Three other studies found IMP3 expression in 45 to 93% of 110 “serous carcinoma cases”, but the type of serous carcinoma was not further specified." (PMID 36740684, 2023). "Immunohistochemistry has revealed strong staining of IMP3 and IMP2 in both ovarian serous carcinoma and tubal cancers and therefore IMP3 and IMP2 may be useful as biomarkers of pelvic high-grade serous carcinoma." (PMID 35706003, 2022). "Prognostic significance of IMP3 could be evaluated only in low grade serous carcinomas in the case of relapse-free survival, where negative cases showed better RFS (p = 0.033)." (PMID 36740684, 2023).
melanoma (5 papers, 2010 to 2016). A malignant, usually aggressive tumor composed of atypical, neoplastic melanocytes. "Recently we reported IMP-3 expression was significantly associated with ALM as compared to other melanoma subtypes and was predictive of poor OS." (PMID 26796627, 2016). "We discovered that IMP-3 expression was positively associated with HMGA2 expression in melanoma cells and tissues." (PMID 26796627, 2016). "In addition, IMP-3 expression was positively associated with high mobility group AT-hook 2 (HMGA2) expression in melanoma." (PMID 26796627, 2016). "It was therefore proposed that IMP-3 played a crucial role in establishing melanomas’ invasive and metastatic ability and hence poor prognosis." (PMID 26796627, 2016). "Twenty-one of 27 (77.8%) strongly pigmented melanomas and 49 of 66 (74.2%) moderately pigmented melanomas expressed IMP-3 in 10% or more of tumor cells." (PMID 26796627, 2016). "Increased IMP-3 expression was described in carcinomas of the colon, kidney and liver, as well as in melanomas." (PMID 26796627, 2016). "Insulin-like growth factor-II mRNA-binding protein 3 (IMP-3) is an RNA-binding protein expressed in multiple cancers, including melanomas." (PMID 26796627, 2016). "IMP-3 expression correlated with thick and high-stage tumor and predicted poorer overall, melanoma-specific, recurrence-free and distant metastasis-free survivals (P = 0.002, 0.006, 0.008 and 0.012, respectively)." (PMID 26796627, 2016). "IMP-3 (hazard ratio 3.67, 95% confidence intervals 1.35–9.97, P = 0.011) was confirmed to be an independent prognostic factor for melanoma-specific survival in multivariate survival analysis." (PMID 26796627, 2016). "IMP-3 staining intensity was also analyzed in these melanoma tissues." (PMID 26796627, 2016). "However, the association of IMP-3 and melanoma-specific survival (MSS) had not yet been defined in acral lentiginous melanomas (ALMs)." (PMID 26796627, 2016). "IMP-3 expression was more likely to be high in stage II (P = 0.031) and III (P = 0.024) than in stage I melanomas." (PMID 26796627, 2016). "IMP-3 bound to and stabilized HMGA2 mRNA and improved the migration and invasion of melanoma cells by regulating HMGA2 expression." (PMID 26796627, 2016). "Functional assays on a subset of these candidates, including MET, ASPM, AKAP9, IMP3, PRKCA, RPA3, and SCAP2, validated their pro-invasion activities in human melanoma cells." (PMID 20520718, 2010). "Further analysis showed that patients with tumor thickness ≤ 4.0 mm and positive IMP-3 expression had a significantly worse melanoma-specific survival than those without IMP-3 expression (P = 0.048)." (PMID 26796627, 2016). "To this end, we selected 6 genes from the candidate list (ASPM, AKAP9, IMP3, PRKCA, RPA3, and SKAP2) based on literature support (see Discussion) to determine whether their knockdown would impact on the invasion of a human melanoma cell, 1205LU." (PMID 20520718, 2010).
osteosarcoma (5 papers, 2012 to 2024). A usually aggressive malignant bone-forming mesenchymal neoplasm, predominantly affecting adolescents and young adults. "Given that Imp3 expression appeared to be associated with an aggressive phenotype of mouse osteosarcoma, we examined the expression in human osteosarcoma." (PMID 23226335, 2012). "Collectively, these results indicated that overexpression of Imp3 conferred growth advantage on osteosarcoma cells under stressful conditions represented by loss of matrix attachment and thereby increased their tumorigenic activity in vivo." (PMID 23226335, 2012). "High level of IGF2BP3/IMP3 expression has been associated with metastatic OS in earlier studies, including in a microarray analysis comparing differentially expressed genes between metastatic and non‐metastatic osteosarcoma cells." (PMID 38561347, 2024). "We also analyzed whether different types of CTCs and IMP3-positive CTCs could be used as auxiliary diagnostic biomarkers for osteosarcoma metastasis." (PMID 36937398, 2023). "Both gain and loss of function of Imp3 in osteosarcoma cells revealed that Imp3 confers the ability to undergo anchorage-independent growth, loss of contact inhibition, and resistance to anoikis in vitro, all of which contribute to the development of tumorgenic potential." (PMID 23226335, 2012). "It was found that high expressions of IMP3 are positively correlated with stage and pulmonary metastasis of osteosarcoma and can be applied as a potential indicator of the malignant degree of osteosarcoma and the prognosis of patients." (PMID 36937398, 2023). "IMP3 plays an important role in the occurrence, development, and prognosis of osteosarcoma, and the expression of IMP3 is considered to be an important feature of osteosarcoma." (PMID 36937398, 2023). "This study demonstrates that the CTCs, especially the IMP3-positive CTCs and H/M-type CTCs, are related to the metastasis of osteosarcoma." (PMID 36937398, 2023). "It has been reported that high expression of IMP3 and VEGF is associated with an increased possibility of lung metastasis, significantly shortened survival time, and stage of osteosarcoma." (PMID 33892656, 2021). "Our findings thus indicate that Imp3 is a potential target for therapeutic control of the aggressiveness of osteosarcoma." (PMID 23226335, 2012). "Our results implicate Imp3 as a key regulator of stem-like tumorigenic characteristics in osteosarcoma cells and as a potential therapeutic target for this malignancy." (PMID 23226335, 2012). "Immunohistochemical analysis of a tissue array containing 40 human osteosarcoma samples showed that IMP3 was expressed in 36 (90%) of the specimens." (PMID 23226335, 2012). "Scoring of staining intensity from 0 to 3 revealed a high expression level (score of 2 or 3) in 27 of the 40 samples (67.5%), suggesting that deregulation of IMP3 expression occurs frequently in human osteosarcoma." (PMID 23226335, 2012). "IMP3 has previously been suggested as a prognostic marker for metastatic or angiogenic potential in human osteosarcoma." (PMID 23226335, 2012). "One mouse injected subcutaneously with AXT-sh1 cells developed lethal osteosarcoma tumors at 49 days after cell injection, and the Imp3 expression in these tumors was markedly increased compared with the parental AXT-sh1 cells." (PMID 23226335, 2012). "The tumors formed after subcutaneous injection of AXT-high cells were larger than those formed by AXT-low cells, suggesting that Imp3 expression is directly related to the tumorigenic activity of osteosarcoma cells." (PMID 23226335, 2012). "Together, these findings indicated that up-regulation of Imp3 in osteosarcoma cells plays an important role in tumorigenesis in vivo." (PMID 23226335, 2012). "The study may provide a new means for comprehensive understanding of osteosarcoma, and the expression of IMP3 gene in CTCs may be a potential new marker for predicting the prognosis of osteosarcoma and inhibition of osteosarcoma metastasis." (PMID 36937398, 2023).
osteosarcoma (continued). "It has been shown that IMP3 is a key regulator of stem-like tumorigenic characteristics in osteosarcoma cells, and its expression is found to confer malignant properties such as anchorage-independent growth, loss of contact inhibition, and escape from anoikic in vitro." (PMID 36937398, 2023). "Compared with the control, IMP3 protein expression increased in osteosarcoma tissues." (PMID 36937398, 2023). "Notably, in these studies, immunohistochemical method was used to detect the IMP3 expression in osteosarcoma tumor tissues, and IMP3 protein is expressed in almost all osteosarcoma tissues." (PMID 36937398, 2023). "Our findings suggest that the up-regulation of Imp3 expression during osteosarcoma formations could be partially attributable to epigenitic modifications." (PMID 23226335, 2012). "Moreover, 90% of the human osteosarcoma specimens analyzed were positive for Imp3 expression." (PMID 23226335, 2012). "Thus Imp3 might be a key regulator of cancer stem-like characteristics in cancer cells, in which case it may also be a potential therapeutic target for osteosarcoma as well as other tumor types." (PMID 23226335, 2012). "We also evaluated the relationships between IMP3 expression in CTCs and EMT phenotypes or tumor metastasis, to investigate the clinical significance of CTCs and IMP3 expression in osteosarcoma." (PMID 36937398, 2023). "The mRNA expression of IMP3 was detected by RNA-ISH assay, and IMP3 protein expression was detected by IHC in normal and osteosarcoma tissues." (PMID 36937398, 2023). "In addition, the relationship between IMP3 expression and the processing of EMT in osteosarcoma CTCs is unclear." (PMID 36937398, 2023). "Furthermore, a study conducted by Kong showed that both the expressions of IMP3 and VEGF in osteosarcoma tissues were higher than that in adjacent tissues." (PMID 35315195, 2022). "The effect of Imp3 on tumorigenicity of osteosarcoma cells did not appear to be mediated through Igf2-dependent mechanism." (PMID 23226335, 2012).